CFAP99 (cilia and flagella associated protein 99)
Tractability: No criterion of Open Targets' tractability assessment is met for any kind of drug.
Gene: Protein-coding gene on chromosome 4 (2,418,955 to 2,463,003, forward strand). Ensembl gene ENSG00000206113.
Subcellular location: Cell projection, cilium, flagellum
Subcellular location (Human Protein Atlas): End piece; Microtubules; Mid piece; Principal piece; Cytokinetic bridge; Mitotic spindle
Gene Ontology:
Cellular component: motile cilium
Genetic constraint (gnomAD): Loss-of-function variants: 71 observed, 71.89 expected, observed/expected ratio (o/e) 0.99, 90% interval 0.81 to 1.2. The synonymous counts are far from expectation, so gnomAD's model fits this gene poorly and the ratio says little. Missense variants: 961 observed, 797.58 expected, observed/expected ratio (o/e) 1.2, 90% interval 1.14 to 1.27. Synonymous variants: 422 observed, 339.89 expected, observed/expected ratio (o/e) 1.24, 90% interval 1.15 to 1.35.
Homologues: Orthologues: chimpanzee CFAP99 (99% identical), macaque CFAP99 (86% identical), pig CFAP99 (75% identical), mouse Cfap99 (73% identical), dog CFAP99 (73% identical), rat Cfap99 (72% identical), rabbit CFAP99 (68% identical), guinea pig CFAP99 (62% identical), tropical clawed frog cfap99 (48% identical), zebrafish cfap99 (39% identical).